INS (insulin)
Diseases named in the same sentence as INS in open-access papers (continued):
Sharing a sentence is not in itself a finding about the gene and the disease.
infection (continued). "After long-term infection, insulin release at 16.6 mM in non-transfected/infected cells decreased 2.8 fold in comparison to non-transfected/non-infected cells at the same glucose concentration (value equal to 100)." (PMID 27631977, 2016). "One week post re-infection, the E4orf1 group, but not the control group showed greater insulin sensitivity, measured as a product of blood glucose and serum insulin." (PMID 27537838, 2016). "Western blotting indicated that the TRAF3 mutation did not influence insulin signalling and TAK1–JNK/NF-κB pathways, unlike in TRAF3 (WT)-treated cells, and had a comparable effect on these molecular events to AdGFP infection." (PMID 26882989, 2016). "After short-term infection, insulin release at 16.6 mM glucose concentration in non-transfected/infected cells significantly increased 1.6 fold in comparison to non-transfected/non-infected cells at the same glucose concentration." (PMID 27631977, 2016). "Insulin secretion in non-infected INS-1E cells either after short-term infection or after long-term infection in absence or presence of L-798106, a specific EP3 antagonist, or NS-398, COX-2 inhibitor, or sulprostone, a specific EP3 agonist, was determined." (PMID 27631977, 2016). "In this study, we used two experimental models, one miming an acute infection (short-term infection) and the other miming a chronic infection (long-term infection) by E. coli of INS-1E cells, able to secrete insulin in response to elevated glucose concentrations." (PMID 27631977, 2016). "Recently, Okabayashi and colleagues published a single-center RCT demonstrating reduction in surgical site infection with intensive vs. moderate BG targets, notable for the very high TIR achieved in the two groups with use of a closed-loop BG monitoring and insulin treatment system." (PMID 25927986, 2015). "The most common reasons documented for DKA in previously diagnosed patients included insulin delivery interruption (e.g. kink in tubing, bent cannula, site issues/ lipohypertrophy) (23.6%), infection (20.0%), and non-adherence (14.5%)." (PMID 25889476, 2015). "Further, infection of differentiated L6 myotubes with Ad-PIMT or Ad-PIMT Ser298Asp but not Ad-PIMT Ser298Ala suppressed insulin stimulated glucose uptake." (PMID 26468734, 2015). "Infection of expanded islet cells with two different ZEB1 shRNA lentiviruses reduced ZEB1 protein levels by up to 85 ± 5%, while significantly elevating insulin transcript levels, relative to cells infected with a control shRNA." (PMID 26264186, 2015). "Furthermore, immunohistochemistry using anti-insulin antibody revealed that some PDA- and PDB-transferred liver cells reacted to the antibody at days 3 and 9 after infection." (PMID 25397325, 2014). "At 2 hours after infection, C3 values were not significantly different, but at 24 hours after infection, insulin-rescued rats demonstrated a 1.7-fold increase compared with diabetic rats (P = 0.01)." (PMID 25610878, 2014). "To determine whether Ets1 inhibited glucose stimulated insulin secretion (GSIS), we overexpressed Ets1 in isolated mouse islets by adenovirus-mediated infection." (PMID 24897113, 2014). "Previous studies have shown that three major highly conserved signal transduction pathways, the nsy-1/sek-1/pmk-1 p38 MAP kinase pathway, the daf-2/daf-16 insulin/IGF1 pathway and the dbl-1/TGF-β signaling pathway, play significant roles in the survival of the host during infection." (PMID 24972867, 2014). "In Bp, we identified several ncRNAs expressed under conditions plausibly linked to mammalian infection, such as BPNC10134F, BPNC20132R, BPNC10175R expressed in normal human serum and BPNC10090R, BPNC20136F, BPNC20142R expressed upon insulin exposure." (PMID 24068961, 2013). "After infection, the cells were cultured in defined conditions with epidermal growth factor (EGF) to promote transdifferentiation and were found to have an active endogenous insulin gene." (PMID 22761608, 2012).
infection (continued). "Infection of MIN6 cells with Ad-control at an MOI necessary to get >90% infection inhibited glucose stimulated insulin secretion (data not shown)." (PMID 22253604, 2012). "Infection also results in increased expression of PI-3 kinase and activation of AKT, suggesting that this infection may induce components of the insulin/IGF-1 receptor cascade." (PMID 19644556, 2009). "Resistin levels, another fat cell-specific secretory factor with insulin-desensitizing properties, were not affected by infection." (PMID 19644556, 2009). "In contrast, infection of INS-1E cells with AdhU2Patient 1 or AdhU2Patient 2 did not modify the insulin secretion levels from control values." (PMID 19065272, 2008). "Although hMSC have previously been shown to express insulin at mRNA level with the infection of recombinant Pdx-1 adenovirus, only a small number of MSCs became insulin positive cells when no gene modification had taken place." (PMID 18628974, 2008). "Moreover, following infection with baculovirus, SHSY-5Y and C3A cells respond to insulin by means of phosphorylation of Akt on serine-473 in the same manner as uninfected cells." (PMID 17309805, 2007). "The leading triggers of DKA were insulin non-compliance (50.5%) and infection (35%)." (PMID 40755641, 2025). "These factors often include missed insulin doses, non-compliance with therapy, and infections." (PMID 41375809, 2025). "Extensive evaluation ruled out infection, noncompliance, and insulin pump malfunction." (PMID 41536411, 2025). "We first determined insulin production in the absence or presence of antagomir without infection." (PMID 39697323, 2024). "However, the interaction between JAK/STAT and insulin signaling during infection has not been firmly established." (PMID 38566182, 2024). "Insulin deficiency may be a consequence of either an absolute lack of availability of insulin, or a significant increase in demand such as in the case of infection." (PMID 37840692, 2023). "So, they might have had an infection, or they’ve not eaten that day, or they’ve taken the wrong dose of insulin." (PMID 35135499, 2022). "During pediatric cardiac surgery, corticosteroids prophylaxis was associated with a shortened CPB time, an increased risk of insulin infusion, and no substantial changes in terms of mortality, ECMO use, postoperative infection, mechanical ventilation time, and ICU LOS." (PMID 35722531, 2022). "Notably, it was in the infection group that we observed a significant increase in the use of basal insulin regimens even though glycemic control has not improved in proportion in this group." (PMID 35315989, 2022). "The infection did not significantly affect insulin activity, GH, or calcitriol content." (PMID 35011946, 2021). "Further studies are needed to determine whether the alteration in insulin metabolism observed in patients is related to a direct effect of CV-B4 or other enterovirus on β cells and/or an indirect effect via IFN-α produced in response to infection." (PMID 34067388, 2021). "It was speculated that omitting skin disinfection before administering subcutaneous insulin injection was not the factor that affected the symptoms of injection site infection." (PMID 33916158, 2021). "Additionally, we found infections and insulin non-adherence as the key drivers to development and presentation with EuDKA." (PMID 33986421, 2021). "A previous study found that the infection rate was significantly lower in patients who were treated with intensive insulin therapy than it was in those without such treatment, but neurological outcome and mortality were not affected by intensive insulin therapy." (PMID 34017305, 2021). "In addition, other events, such as stress or infection, can significantly change glucose homeostasis independent of insulin sensitivity." (PMID 33004691, 2020).
infection (continued). "However, in all infection cases as opposed to the regular or normal days, blood glucose levels were elevated for a prolonged period despite higher insulin and reduced carbohydrates intake." (PMID 32784178, 2020). "Death of insulin-producing β cells, although present, may not account for all the transcriptional changes that follow infection, consistent with the concept that β cells remain viable but lose function early in the course of T1D onset." (PMID 32093375, 2020). "In addition, it has been shown that insulin signaling interacts with the TGF-ß signaling in the absence of infection." (PMID 32610560, 2020). "Infection-induced anomalies are characterized by violation of the norm of blood glucose dynamics, where blood glucose remains elevated despite taking a higher amount of insulin injection with less carbohydrate consumption." (PMID 32784179, 2020). "Furthermore, a study found that (insulin–gastrin) INS-GAS mice coinfected with H. pylori and Streptococcus salivarius developed more severe gastric inflammation than did H. pylori only at 5 months post-infection." (PMID 31781514, 2019). "One key difference is that the acute phase response, which is a rapid inflammatory response that protects against infection using non-specific defence mechanisms, was activated and sustained through the EL stage in insulin-sensitive individuals but not in insulin-resistant individuals." (PMID 31142858, 2019). "Patients in CHO groups presented a lowerincidence of hospital infection (RR=0.29, 95% CI 0.09-0.94;P=0.023), needed fewer vasoactive drugs during surgeryand ICU stay (P<0.05); and had better blood glucoselevels in the first six hours of recovery (P=0.015),requiring less exogenous insulin (P=0.018)." (PMID 30916121, 2019). "Infection with wild-type V. cholerae but not a V. cholerae ΔgcvT mutant leads to accumulation of lipid droplets in the intestine, depletes lipid droplets in the fat body, and suppresses signaling through the insulin pathway (IIS)." (PMID 28586382, 2017). "Insulin for T2D should only be used when no other treatment is available, to prevent short-term acute complications (such as hyperosmolar coma or ketoacidosis in case of an infection) or when the lack of insulin per se assigns patients in a high risk group." (PMID 27391319, 2016). "At 2 hours after infection C5a levels were not significantly different between the groups, but at 24 hours after infection, C5a concentrations increased to 2-fold greater for insulin-rescued rats compared with diabetic rats (P = 0.02)." (PMID 25610878, 2014). "Genetic and biochemical experiments revealed that lin-7 modulates the DAF-2 insulin/IGF-1 signalling pathway, by binding directly to the DAF-2 RTK via LIN-2, and that both daf-16 and hsf-1 are required for the enhanced survival exhibited by lin-7 mutants upon infection." (PMID 22672310, 2012). "However, as the shift in survival time during infection of upd2∆upd3∆ flies with ∆MAB_1132c strains was not replicated in flies lacking IPCs, this difference in host survival is not a product of differential insulin pathway disruption." (PMID 39514319, 2024). "Our data showed that insulin secretion induced by circulatory lipids (HDL and fatty acids) did not reduce the levels of blood glucose in infected adult mice, suggesting that lipid-storing adipocytes may be compromised and dysfunctional in regulating blood glucose levels during infection." (PMID 35329973, 2022). "Current research shows that an induction of AMP production may activate insulin and insulin-mediated phosphatidylinositol-3-kinase (PI3K)/protein kinase B (AKT) transduction pathways and consequently enable urinary tract epithelial cells to avoid UPEC invasion and infection." (PMID 36555403, 2022). "Therefore, infections with CVB4 can modulate the expression of thymic IGF2, which strengthens the hypothesis of a possible role of CVB infections in decreasing central tolerance to insulin." (PMID 34072590, 2021).
infection (continued). "An increased trend of infection (but not significantly different) was observed after pretreatment with hydrocortisone (42 ± 34 infected cells per well, (p = 0.6), spermidine (50 ± 6 infected cells per well, p = 0.052), and porcine insulin (46 ±27 infected cells per well, p = 0.4)." (PMID 32260595, 2020). "Consequently, using INS-1 832/13 rat β-cell line, we found that overexpression of GAS5 by lentivirus infection increased glucose-stimulated insulin secretion and insulin content compared with negative control, whereas knockdown of GAS5 expression reduced both them." (PMID 33195407, 2020). "We hypothesized that an increase in insulin synthesis after short-term infection could be the initial response to infection of cells with the activation of phospholipases and COX-2, releasing PGE2, which, in balanced amounts inside the cell, would have a stimulatory effect on insulin secretion." (PMID 27631977, 2016). "Indeed, we did not observe changes in hepatic insulin signaling with Ad-TCF7L2 infection in lean mice, suggesting that TCF7L2 might not directly regulate insulin signaling in the physiological context (data not shown)." (PMID 23028378, 2012). "We next determined if treating pancreatic β cells with the hsa-miR-AMC1 antagomir alters insulin secretion in a high-glucose environment, without and with CVB4 infection." (PMID 39697323, 2024). "In patients without infection, there was a near correction of PCT levels and white blood cell count following insulin administration and glycemia correction." (PMID 37510185, 2023). "Two weeks post-infection, mice were treated with or without Dex in their drinking water for 1 week, an IPGTT was performed, and blood was collected to measure plasma insulin levels." (PMID 37253782, 2023). "Levels of both regular and phosphorylated JAK1 significantly increased in ST cells upon their infection with TGEV, but not after treatment with IGF-1 or insulin." (PMID 35215353, 2022). "Overall, infection (32.6%) was the most common trigger for DKA, followed by insulin non-compliance (13.7%)." (PMID 33986421, 2021). "Therefore, insulin may reduce the adhesion and invasion of UPEC to bladder cells by affecting glucose homeostasis inside and outside the cell, and decrease the augmentation of JAK/STAT pathway-mediated inflammation and infection in bladder cells in a high-glucose environment." (PMID 34946023, 2021). "Unlike in developed countries, where infection is the most common precipitating factor for DKA, insulin disruption/omission was the major precipitating factor for DKA in the studied patients (34.8%)." (PMID 31722517, 2020). "In diabetic rats (DATCC), infection resulted in the expression of ICAM-1 and P-selectin, but not of PECAM-1, and insulin treatment did not alter this pattern." (PMID 30705678, 2018). "Insulin treatment did not induce increased cytokine production against the infection in diabetic mice, although mice from both the control group and the diabetic group infected by Pb18 showed increased production of TNF-α after insulin treatment." (PMID 30426021, 2018). "Although the exact interaction between the insulin signalling pathway and HSF-1 during infection is not yet well characterized, recently, this interplay has been dissected in the context of ageing." (PMID 22672310, 2012). "On the other hand, although infection with an adenovirus producing GFP did not modify beta cell development, the relative number of insulin-positive cells was reduced in pancreases infected with an adenovirus producing dnChREBP." (PMID 22760788, 2012). "Since infection of SHSY-5Y and C3A cells with baculovirus apparently did not influence the phosphorylation of Akt, the response to insulin following infection was investigated." (PMID 17309805, 2007).
infection (continued). "Beyond the noted heightened insulin requirements mentioned in the study, the fundamental treatment strategies and post-treatment outcomes did not exhibit significant differences from those children suffering DKA without infection." (PMID 38287388, 2024). "Serum insulin and glucose levels were not different in RSV-infected mice 6 days post infection." (PMID 36768699, 2023). "Infection (32.6%) was the most common trigger for DKA, followed by insulin nonadherence (13.7%)." (PMID 35614469, 2022). "Infection with the ATCC 25923 strain (CATCC and DATCC) did not alter IL-6 levels, but treatment with multiple doses of insulin increased IL-6 production (7- to 6-fold) in the PeLF from infected diabetic rats (DATCC+i2) compared with that of non-insulin-treated animals (DATCC)." (PMID 30705678, 2018). "Neither insulin tolerance nor plasma insulin levels was changed with expression of TCF7L2, suggesting that global insulin signaling might not be affected by Ad-TCF7L2 M infection." (PMID 23028378, 2012). "Moreover, we show that suppression of insulin signaling in muscles by upd/JAK/STAT/ImpL2 signaling is a fundamental host response to immune challenge, without which the animal is unlikely to overcome the infection." (PMID 38566182, 2024). "The results show that pretreatment of primary enterocytes with hydrocortisone, spermidine, porcine insulin, Wnt agonist, and intestinal contents could stimulate the expression of APN and enhance the infection of PEDV CV777 Vero adapted and non-adapted strains and the TGEV Miller in the enterocytes." (PMID 32260595, 2020). "In a mouse model of experimental TB, no changes in serum insulin levels were observed upon infection (uninfected: 1.70 ± 0.46 ng/ml; Mtb: 4.14 ± 2.94 ng/ml; data representative of 3 independent experiments; 4 to 5 animals per group) indicating that CD8+ T cells do not induce insulin resistance." (PMID 29040326, 2017).